SLC71A3P (solute carrier family 71 member 3, pseudogene)
Synonyms: MGC12945; formerly HIATL2; MFSD14C; MFSD14CP
Gene: Transcribed unprocessed pseudogene on chromosome 9 (96,949,555 to 97,013,366, reverse strand). Ensembl gene ENSG00000196312.
Subcellular location: Membrane